CGAS (cyclic GMP-AMP synthase)
Diseases named in the same sentence as CGAS in open-access papers (continued):
Sharing a sentence is not in itself a finding about the gene and the disease.
cancer (continued). "In the context of cancer immunotherapy, ACLY inhibition has been reported to overcome immunotherapy resistance through polyunsaturated fatty acid peroxidation and activation of the cGAS-STING pathway." (PMID 39399493, 2024). "The Stimulator of Interferon Genes (STING) pathway, alongside cyclic guanosine-adenosine triphosphate synthase (cGAS), is widely expressed across various cell types, including immune, non-immune, and cancer cells." (PMID 38817608, 2024). "Hence, it is critical to understand RLR and cGLR (cGAS/STING signaling) interaction during different infections and inflammatory diseases, such as autoinflammation and cancers." (PMID 38339107, 2024). "To confirm whether the cGAMP transferred from cancer cells is responsible for the activation of STING pathway and consequent production of IFNβ in MSCs, we knocked out cGAS in MB231 and MCF7 cells." (PMID 38638003, 2024). "The cGAS-STING pathway is a senescence driver and a modulator of cancer cell rejection by the immune system; as such, cancer cells may benefit from inactivating this pathway." (PMID 39682179, 2024). "By leveraging the immunogenic properties of nuclear necroptosis and the interaction between ZBP1 and the cGAS-STING pathway, it may be possible to develop novel strategies for cancer treatment that enhance immune responses against tumors." (PMID 38523155, 2024). "The cGAS-STING pathway is a sensor for cytosolic double stranded DNA (dsDNA) in central cells that allows innate immunity to respond to infection, inflammation, and cancer." (PMID 39403369, 2024). "Considering the age-related nature of PCa and the involvement of the cGAS-STING pathway in both aging and cancer, as indicated by our previous study, we have conducted an analysis of molecular subtypes and identified key genes for PCa through the lens of the cGAS-STING pathway." (PMID 38877472, 2024). "cGAS, a known sensor of foreign DNA in pathogens and tumors, and known to activate type I IFNs by STING, has recently attracted attention as a good target for cancer therapy." (PMID 38898119, 2024). "Furthermore, it has been shown that sub-cytotoxic concentrations of Top1 poisons can activate the cGAS/STING pathway and immune gene expression in cancer cells, and this process is mediated by the induction of micronuclei in an R-loop-dependent manner." (PMID 39215193, 2024). "Importantly, the interest in IFNs role in modulating the immune system in cancer can partly be credited to the exploration of how innate immune pathways, and in particularly how the cGAS-STING DNA-sensing pathway is involved in anti-cancer biology." (PMID 40012911, 2024). "The cGAS-STING pathway is a crucial component of the innate immune system, responsible for detecting cytosolic double-stranded DNA (dsDNA), which indicates infections, cellular damage, or cancer." (PMID 40018367, 2024). "cGAMP transfection in NCI-N87 cells rescued the upregulation of HLA-DR in TDDCs following T-DXd treatment, which was attenuated in the absence of cancer cell-intrinsic cGAS." (PMID 39449023, 2024). "Another reason to study the cGAS-STING and interferon signaling is that it may sensitize cancer patients to immunotherapy." (PMID 38167507, 2024). "Thus, cGAS/STING signaling regulates tumorigenesis and cancer cell proliferation and metastasis depending on the cancer stage and type." (PMID 38339107, 2024). "Based on these observations, it is plausible that cancer-specific disruptions in MRN, cGAS, STING and/or ZBP1 may influence responses to DNA damaging therapy and immunotherapy, warranting further exploration of their clinical implications." (PMID 38200309, 2024). "Since the discovery that cGAS/STING recognizes endogenous DNA released from dying cancer cells and induces type I interferon and antitumor T cell responses, efforts to understand and therapeutically target the STING pathway in cancer have ensued." (PMID 38226619, 2024).
cancer (continued). "Similarly, 87.5% of the 103 HCC patients from our hospital (EHBH) showed positive expression of cGAS in cancer cells, while only less than 9% of the patients displayed positive STING expression in cancer cells." (PMID 38177099, 2024). "For example, PtII triphenylamine complexes 11 and 12 could damage mitochondrial/nuclear DNA and the nuclear envelope to activate the cGAS-STING pathway, inducing pyroptosis in cancer cells and an intense anticancer immune response in vitro and in vivo." (PMID 38999073, 2024). "Mitotic mis-segregation of chromosomal fragments into micronuclei that accumulate and rupture in BRCA1-deficient cells can give rise to cytosolic dsDNA that stimulates cGAS-STING and inflammatory signaling, which may drive cancer initiation." (PMID 39159817, 2024). "In this line, current clinical trials evaluating drugs targeting the cGAS/STING pathway are primarily focused in cancers with no viral etiology." (PMID 38675916, 2024). "Indeed, our data demonstrate that targeting TREX1 not only enhances the sensitivity of chemoresistant SCLC to chemotherapy in vitro and in vivo but also activates the cGAS-STING pathway, producing an antiviral response in cancer cells." (PMID 39177280, 2024). "Additionally, we highlight the importance of the cGAS–STING pathway in anti-pathogen immunity and summarize the advances in the current research targeting this pathway in various disorders and cancers." (PMID 37686127, 2023). "Activation of the cGAS-STING pathway plays a central role in immune response pathways, regulating autophagy, and promoting senescence in damaged cells, all of which are important mechanisms for dealing with damaged cells and cancers." (PMID 38161589, 2023). "The activation of the cyclic guanosine monophosphate-adenosine monophosphate synthase-stimulator of interferon genes (cGAS-STING) signaling pathway has attracted great attention for its ability to up-regulate innate immune response and thus enhance cancer immunotherapy." (PMID 37061706, 2023). "Lastly, we provide an outlook on how cGAS-STING and autophagy can be combined, with the hope that our research can help people better understand their potential roles in cancer immunity and bring light to the treatment of cancer." (PMID 36936940, 2023). "Therefore, in this review, we systematically discuss the interaction between the cGAS-STING signaling pathway and autophagy in cancer immunity, hoping to provide a direction for exploring new cancer immune mechanisms and therapeutic approaches." (PMID 36936940, 2023). "Epigenetic remodeling in the cancer landscape can lead to mobilization of the TEs which are also ligands of innate immunity particularly of RNA via TLR3, RIG1, and MDA5 receptors, of DNA via TLR3/7/8, and cGAS." (PMID 37854446, 2023). "Despite acute activation of cGAS/STING provides undoubted benefits against pathogens and cancer cells, a chronic activation may result in an IFN-driven systemic inflammation, inducing a cytokine storm (cytokine release syndrome), similarly to sepsis." (PMID 37298177, 2023). "More importantly, even in absence of functional STING, cGAS-dependent production of cGAMP in the different cancer cell types was proven to be crucial for the activation of an efficient antitumor immune-response both in vitro and in-vivo." (PMID 37180110, 2023). "Therefore, cGAS, STING, and AIM2 have attracted attention as drug discovery seeds in the cancer immunotherapy field." (PMID 37046775, 2023). "A previous study reported that cancer‐cell‐intrinsic expression of cGAS, but not STING, promoted the infiltration of effector CD8+ T cells and consequently resulted in prolonged survival." (PMID 37986544, 2023). "In addition to innate immunity, cGAS-STING also drives autophagy, cell survival, infection, inflammation, cancer, and senescence pathways." (PMID 37854446, 2023).
cancer (continued). "Therefore, the interplay among the DNA damage response, cGAS-STING pathway activation, and anti-tumoral immunity is critical to reveal novel targets for future cancer immunotherapies." (PMID 36894542, 2023). "Through these stages, the cGAS-STING pathway becomes a central link between immunity and cancer." (PMID 37448962, 2023). "Therefore, inhibiting DNA repair and promoting DDR progression, which activates the cGAS-STING pathway, present promising avenues for cancer therapy." (PMID 37448962, 2023). "Likewise, Li and colleagues demonstrated that certain stimuli, such as genotoxic stress, activate the cGAS/STING pathway, which can trigger unwanted cellular responses such as cellular senescence, inflammation, or cancer." (PMID 37108510, 2023). "Therefore, it is necessary to elucidate the shift from a promoter to a protector role of the cGAS-STING pathway in the transition from intestinal inflammation, cancer, infections and tissue repair." (PMID 37781354, 2023). "Indeed, we found that inhibition of ATM led to a robust increase in the expression of cGAS, the phosphorylation of STING and TBK1 in a variety of human cancer cell lines, including HeLa, H157, H1299, A549, MDA-MB-231 and BT549." (PMID 36778120, 2023). "The cGAS-STING pathway can be activated by radiation-induced DNA damage and because of its important role in anti-cancer immunity activation, to increase its activation in cancer cells could provide significant therapeutic benefits for patients." (PMID 37355491, 2023). "Besides DNA from these sources, the cGAS-STING is also activated by extracellular, mitochondrial, and nuclear DNA, including increased cytosolic DNA levels in cancers." (PMID 38250078, 2023). "Recently, cGAS-STING and autophagy have been shown to be interconnected, which may influence the progression of cancer." (PMID 36936940, 2023). "Therefore, inhibiting DNA repair and promoting DDR progression, which activates the cGAS-STING pathway, represents a promising avenue for cancer therapy." (PMID 37448962, 2023). "Based on this, we systematically sorted out the recent findings of cGAS-STING and autophagy in cancer immunity and explored the interactions between cGAS-STING and autophagy, although these interactions have not been extensively studied." (PMID 36936940, 2023). "The cGAS-STING-IRF3 pathway has been highlighted as an important regulator of viral DNA recognition for successful host defence, which is issued as a powerful pathway for cancer treatments." (PMID 37162544, 2023). "Given that the cGAS/STING pathway is a natural immune regulator disrupted by traditional cancer therapies, modulating it through targeted therapies has excellent potential to develop adjunct therapies against cancer." (PMID 37380989, 2023). "Therefore, cGAS-STING targeting therapy needs to be delicately employed depending on the type, characteristics, and metastatic status of cancer." (PMID 37354378, 2023). "Interestingly, cGAS-STING is known to promote immune responses against tumors, and is being explored for its potential use in cancer immunotherapy applications." (PMID 37627155, 2023). "It is worth noting that the cytosolic dsDNA sensing pathway, especially the cyclic GMP-AMP synthase and stimulator of interferon genes (cGAS-STING) pathway, is usually epigenetically silenced in human cancers through DNA hypermethylation at their promoter regions." (PMID 36600243, 2023). "Various studies have demonstrated that epigenetic silencing of cGAS and STING genes, rather than mutation, occurs in different types of cancer." (PMID 38203626, 2023). "Intriguingly, inactivation of key components in this signalling route, such as cGAS, STING, TBK1, and IRF3, also increases micronuclei formation and chromosome mis-segregation, exemplifying the multifaceted role of cGAS-STING signalling in cancer." (PMID 38067140, 2023).
cancer (continued). "It is essential to develop a comprehensive understanding of the activation of the cGAS/STING pathway, which may possess both antitumor and protumor roles depending on the cancer type and stage of cancer progression." (PMID 37354378, 2023). "Intriguingly, the cGAS/STING-mediated inflammatory response also appears to provide a targetable vulnerability of cancer cells with induced CIN, as cGAS-STING promotes IL-6-STAT3 pro-survival signalling, presumably for cells to cope with the initial stress response that is imposed by CIN." (PMID 38067140, 2023). "In this paper, we will focus on the non-innate immune system pathways, in which the cGAS-STING pathway also plays an important role in cancer." (PMID 37965570, 2023). "More interestingly, our recent investigation revealed that cGAS-STING could be activated in severe DNA damage; however, SASP activity has been shown to alternatively mediate DNA autophagy in protecting cancer cell survival." (PMID 36061145, 2022). "Thus, the cGAS-STING pathway is critical in many disease processes, including autoimmune diseases, inflammatory diseases, degenerative diseases, and cancer." (PMID 36741390, 2022). "In summary, we present a “basal flux” mechanism for tonic cGAS-STING signalling, regulated at the level of post-Golgi STING trafficking, which could be exploited for cancer immunotherapy." (PMID 36379959, 2022). "Supporting these facts, we found that passenger EV-DNA associates with the endosome–lysosome compartment and cytoplasmic DNA sensors (cGAS/STING) in the recipient cells, which may have an important role in cancer." (PMID 35565197, 2022). "Two subsequent studies determined the extensive transcriptional characteristics of innate immune genes based on the cGAS–STING pathway in cancer cells lacking BRCA1 or BRCA2." (PMID 36613695, 2022). "Thus, TTFields activate the cGAS/STING inflammasome in GBM and other cancer cells, leading to increased production of PICs and T1IFNs in a STING-dependent manner." (PMID 35199647, 2022). "Moreover, the cGAS-STING pathway is responsible for the innate immune detection of cancer, thus playing an important role in anti-cancer immunity, as well as potentiating the effects of cancer immunotherapy." (PMID 36612217, 2022). "In cancer cells undergoing ICD, type I interferons (IFN-Is) are released by mechanisms involving the detection of endogenous nucleic acids, i.e., dsRNA by TLR3, or dsDNA by cyclic GMP-AMP synthase (cGAS)." (PMID 36015189, 2022). "Our analysis of mutation rates showed that the four STING pathway genes (cGAS, STING, TBK1 and IRF3) were usually not mutated in human cancers, with a complete absence of homozygous loss-of-function mutations in almost all cancer types." (PMID 35794238, 2022). "The cGAS/STING pathway and activation of T1IFNs also plays critical roles in cancer." (PMID 36387071, 2022). "Notably, cGAS-STING-agonists act in combination with immune checkpoint targeting drugs (CTLA-4, PD-1, PD-L1) to induce potent cancer eradication." (PMID 35655772, 2022). "We further hypothesize that tumors with high CIN and functional cGAS-STING pathway can mount a more effective immune response, but that an adaptive CD8 response still requires cancer neoantigens." (PMID 36923311, 2022). "Herein, we briefly review the current knowledge on the dichotomous functions of cGAS–STING in the TME, emphasizing that rigorous understanding of the mechanism governing this pathway in cancer is critical for the successful clinical translation of STING-directed therapies." (PMID 35325182, 2022). "Moreover, mtDNA digestion with DNase I and autophagy inhibition with chloroquine attenuates the cGAS-STING pathway activation and ESCC cancer growth." (PMID 35209954, 2022). "Emerging evidence indicates that the cyclic GMP-AMP synthase (cGAS)-stimulator of interferon genes (STING) axis is a major innate immune pathway involved in generating spontaneous antitumor T cell responses and thus a promising cancer immunotherapy target." (PMID 36559204, 2022).
cancer (continued). "Chitosan and COS have also been suggested to promote innate and adaptive immune response by promoting the cGAS-STING-dependent induction of type 1 interferons in dendritic cells, the inhibition of PI3K-AKT signaling involved in cancer proliferation and survival, and the induction of apoptosis." (PMID 35631632, 2022). "Numerous recent studies have shown that the cGAS-STING signaling pathway is an ideal target for therapeutic intervention in diseases, especially in cancer and tumors, which may provide new ideas for combating herpesvirus." (PMID 35844623, 2022). "cGAS/STING axis is the major executor of cytosolic dsDNA sensing that leads to the production of type I interferon (IFNI) not only upon bacterial infection, but also in cancer cells, upon DNA damage." (PMID 36572679, 2022). "Interestingly, it has been observed that cGAS and/or STING expression is decreased in various cancers, like—colon cancer and melanoma." (PMID 35903542, 2022). "Although chemokine expression in PNETs has been poorly studied, upstream signaling pathways including NF-κB and canonical cyclic GMP-AMP synthase/stimulator of interferon genes (STING) pathways have been shown to regulate CCR5 and CCL5 expression in other types of cancer." (PMID 36301668, 2022). "Activation of the cGAS-STING pathway can induce the expression of type I IFNs and other cytokines, and conduct the signals to the nucleus, which makes the cGAS-STING pathway a promising target for cancer immunotherapy." (PMID 35889509, 2022). "Indeed, current clinical trials are based on a combination of cGAS–STING pathway agonists with immune checkpoint inhibitors, such as pembrolizumab, ipilimumab, and nivolumab, for cancer immunotherapy." (PMID 35267494, 2022). "From 2013 to 2021, the foci of research on the cGAS-STING pathway has changed from the basic mechanism to treatments of diseases via the cGAS-STING pathway, especially cancer and nanoparticle, these would be hotspots of research recently and in the near future." (PMID 35720348, 2022). "Micronuclei are recognized by the immune sensor axis cGAS/STING, driving cancer metastasis." (PMID 35393399, 2022). "We also calculated the enrichment of a cGAS-STING signaling pathway, which may be involved in regulating inflammatory responses and cancer progression in AT2 cells of PR mice." (PMID 35892659, 2022). "CIN plays a multifaceted role in cancer, and its microenvironment, for instance, by introducing double-stranded DNA into the cytosol, CIN could engage the cGAS–STING antiviral pathway to facilitate inflammatory signaling." (PMID 35419410, 2022). "Cancer CIN and genotoxic chemotherapy may both result in genomic DNA fragments leaking into the cytoplasm and activation of cGAS." (PMID 36923311, 2022). "mtDNA stress may contribute to the cGAS-STING pathway activation and type 1 interferon responses in various pathological states, including infectious diseases, cancer, neurodegeneration, and other mitochondria-related illnesses." (PMID 35979145, 2022). "Moreover, it is essential to continue investigating the effects of the cGAS/STING pathway and its implications in both the radiotherapy response and immune response in human cancers." (PMID 36387071, 2022). "Similar to chemotherapeutics, radiotherapy can trigger cGAS-STING signalling axis through the generation of neo-epitopes, which would activate dendritic cells and through the cytoplasmic DNA accumulation directly trigger cGAS-STING in cancer cells." (PMID 33922087, 2021). "cGAS/STING signaling plays an antitumor role in cancer cells in both an autonomous and non-autonomous manner." (PMID 35046953, 2021). "DNA mismatch repair (MMR) inactivation-induced neoantigens in cancers boost adaptive immunity as well, which is independent of the cGAS–STING pathway." (PMID 33791310, 2021).